FGF2 (fibroblast growth factor 2)
Diseases named in the same sentence as FGF2 in open-access papers (continued):
Sharing a sentence is not in itself a finding about the gene and the disease.
tumor (continued). "Conversely, FGF-2 rescued the growth of IM-naive GISTs treated by IM and protected them from IM-induced apoptosis, consistent with the possible involvement of FGF-2 in tumor response to IM-based therapy." (PMID 32599808, 2020). "Moreover, CAFs produce matrix metalloproteases 1 and 2 (MMP1 and MMP2) and FGF2, shaping the ECM structure and promoting tumor cell survival, respectively." (PMID 33167307, 2020). "Finally, FGF2 exerts a synergistic effect with PDGF-BB to increase the interaction between endothelial and mural cells, and promote tumor angiogenesis and metastasis." (PMID 32993787, 2020). "Similar to E0771, FGF-2 expression did not significantly affect tumor cell growth rate in vitro and VEGF and PDGF-B expression." (PMID 32709869, 2020). "We therefore hypothesized that FGF2 could be used to antagonize the effect of TGF-β in PSC activation and thereby inhibit the tumor stroma induced pro-tumorigenic functions." (PMID 31911892, 2020). "Subsequent cultivation within Dulbecco’s Modified Eagle’s Medium/Ham’s -F12 supplemented with epidermal growth factor (EGF), fibroblast growth factor 2 (FGF-2), B27 and 10% fetal calf serum (FCS) led to an adherently growing cell culture for both tumor tissue samples." (PMID 32927768, 2020). "Another study showed that PPARα ligands may suppress angiogenesis indirectly by inhibiting tumor cell production of VEGF and FGF2 and by increasing thrombospondin-140." (PMID 32616724, 2020). "In our hands blocking FGF2 or its absence did not have a generalisable effect on tumour vascular density before or after radiation." (PMID 32792542, 2020). "Treatment with the blocking anti-FGF2 antibody did not affect tumour growth or macrophage polarisation unless irradiation had been applied, similar to the tumours formed from high innocula in Fgf2LMW−/−mice." (PMID 32792542, 2020). "These were unexpected findings because neither drug monotherapy significantly inhibited FGF-2+ tumor growth." (PMID 32709869, 2020). "While FGF2 was a chemoattractant for human and murine OPCs, anosmin-1 only attracted OPCs isolated from tumor samples and repelled those from non-tumoral samples." (PMID 32498223, 2020). "Vascular size was notably reduced by FGF2 blocking antibody in irradiated SW1222 but not in MC38 tumours." (PMID 32792542, 2020). "On the contrary, DDAH1 in tumors exhibited a negative correlation with another angiogenic factor, FGF2, and DDAH2 in tumor-adjacent tissue—a positive association with an angiostatic IP-10." (PMID 32872669, 2020). "To test this possibility, we treated 48 hpf zebrafish larvae with bFGF, also known as FGF-2, which is able to bind Fgfr1-3 and is involved in various biological processes, such as cell proliferation, angiogenesis, differentiation, and tumor development." (PMID 31123246, 2019). "Interestingly, varying PF4 secretion can significantly elevate the levels of unbound FGF2 and unbound VEGF in tumor tissue." (PMID 31379588, 2019). "Furthermore, we observed that TECs treated with TGF‐β were more competent in promoting in vivo tumor growth than TECs treated with TGF‐β and FGF2." (PMID 31094056, 2019). "Upregulated expression of various canonical FGFs (including FGF1, FGF2, and FGF 6–9) derived from tumor cells or stromal cells induces tumor progression in various cancers; however, the effects of circulating hormone-like FGFs (such as FGF19, FGF21, and FGF23) on tumors are unclear." (PMID 31408968, 2019). "In addition to the increase in FGF2 production by LX‐2, expression of FGFRs is also elevated in cell lines treated with BET inhibitors and importantly in patient tumor specimens following progression on PLX51107 treatment." (PMID 30610113, 2019). "FGF-2 and TGF-β are produced by tumor cells, and play important roles in antiangiogenic resistance." (PMID 31438982, 2019).
tumor (continued). "As a tumor is often described as being like a “chronic wound”, the hypoxic conditions and high concentration of cytokines and growth factors IL-1α, IL-1β, IL-6, FGF-2, IGF-1, TGF-β, VEGF-A, HIF-1α, EGF, TGF-α are a likely trigger for MSCs recruitment to tumor microenvironments." (PMID 31569731, 2019). "The role of TAMs and mast cells in tumor progression and angiogenesis was demonstrated by their capacity of releasing several proangiogenic cytokines such as VEGF, IL-8, fibroblast growth factor 2 (FGF-2), and TNF-alfa." (PMID 31934533, 2019). "Therefore, incorporating FGF2 and PF4 provides a more complete view of the angiogenic interaction network and a more comprehensive understanding of tumor angiogenic state, as compared to previous models." (PMID 31379588, 2019). "In addition, by producing pro-angiogenic factors, such as fibroblast growth factor 2 (FGF2) and VEGFA, CAFs regulate angiogenesis in the stroma, thereby providing essential nutrients for highly proliferative tumor cells." (PMID 31106200, 2019). "However, PlGF signaling can indirectly contribute to the tumor angiogenic switch by upregulating the expressions of other angiogenic factors (VEGF-A, FGF2 and MMPs)." (PMID 31216652, 2019). "Moreover, expression of fibroblast growth factor 2 (FGF-2) increases significantly and initiates cancer proliferation and tumor vascular angiogenesis." (PMID 30927928, 2019). "In details, the decrease of FGF2, FLT1, CCL2 mRNA, along with increase of SERPINF1 mRNA were observed in EP300 knockdown ESCC cells, predicting that EP300 may promote tumor initiation via angiogenesis in ESCC." (PMID 31632486, 2019). "In particular, CAFs differentiation can be induced by tumour cell-derived transforming growth factor β (TGF-β), epidermal growth factor (EGF), PDGFα, PDGFβ, basic fibroblast growth factor (bFGF, also known as FGF2), interleukin 6 (IL-6), and interleukin 1β (IL-1β)." (PMID 29967776, 2018). "The interference of FGF-2 with HPSE as well as TGF-β and IGF-2 for CD222 activity in the tumor microenvironments may modulate epithelial-mesenchymal interactions." (PMID 30333909, 2018). "Collectively, these data indicate that CCDC115 expression could be impeding tumor growth in our current study via several mechanisms, including disruption of the EGFR or FGF2/MAPK pathways." (PMID 29890952, 2018). "As a consequence of the anti-FGF2/anti-angiogenic activity of PTX3, FGF2-dependent syngeneic tumor grafts of different origin were characterized by impaired FGFR1 activation and reduced CD31+ vascularization and tumor growth when injected in TgN(Tie2-hPTX3) mice." (PMID 30349543, 2018). "Moreover, expression of transforming growth factor β1 (TGFβ1) and fibroblast growth factor 2 (FGF2) even decreased in ASC.B6, opposing to the increased tumor growth promoting effect." (PMID 30185144, 2018). "In conclusion, FGF2/PTX3 interaction may exert a deep impact on the angiogenesis process during inflammation and tumor growth." (PMID 30349543, 2018). "Indeed, FGF2 expression increased in IM-resistant GIST cells in vitro and in tumor specimens from IM-resistant GIST patients." (PMID 30326595, 2018). "3T3 fibroblasts were genetically propagated to become tumorigenic by introducing H-Ras17, and used as FGF-2 negative tumor." (PMID 29423271, 2018). "Moreover, treatment of MSCs with supernatants from PC3 cells, leading to tumor-educated MSCs (TE-MSCs), increased the secretion of IL-6, CCL5, VEGF and FGF-2 by MSCs and increased their capability to increase PC3 cells clonogenic growth." (PMID 28477013, 2017). "The functional roles of PKCα/δ modulation of Sur8 were further delineated by the inverse regulation of Sur8 and PKCα/δ levels by FGF2, and the inverse expression levels of Sur8 and PKCα/δ in normal and tumor tissues of CRC patients." (PMID 29383184, 2017).
tumor (continued). "Targeting the MAPK signal transduction pathway through the targeting of the FGF2, FGF9, MECOM, PLA2G4C and PRKACB might increase tumor responsiveness to irinotecan treatment." (PMID 28749961, 2017). "In addition, PERK-mediated upregulation of fibroblast growth factor 2 (FGF2), vascular endothelial growth factor (VEGF), and interleukin-6 (IL-6) and downregulation of antiangiogenic cytokines remarkably promote tumor growth and vascularization." (PMID 29430279, 2017). "M2 macrophages not only inhibit tumor apoptosis and promote cell proliferation by activating NK-κB, but participated in tumor metastasis by releasing diverse pro-angiogenic factors such as VEGF, FGF2 and TNFα." (PMID 29152078, 2017). "Towards this end, KO/PyMT and WT/PyMT tumour cells were grown in 10% fetal bovine serum (FBS)-media in the presence/absence of high concentrations of HSPG-binding growth factor FGF2 or non-HSPG-binding growth factor EGF." (PMID 28102194, 2017). "Interestingly, host cell expressions of several markers were strongly upregulated towards the tumour bulk, but hardly visible outside the tumour region, including Vimentin and the angiogenic factors Angiopoietin 2, VEGF and FGF2." (PMID 28173797, 2017). "FGF2 (over)expression in tumor and non-tumor cells was observed after chemo- and radio-therapy, associated with radio- and chemo-resistance, correlated with an increased risk of recurrence and reduced overall survival." (PMID 29206199, 2017). "Whether this finding could be due to a race-related difference in the tumor’s responsiveness to bevacizumab is deserving of further study to fully evaluate if ANGPT1, ANGPT2, TEK, FGF2, MMP9 and VEGFA are promising targets for future research." (PMID 28045923, 2017). "For example, miR-15/miR-16 cluster members (chromosomes 3 & 13) and their correlated growth factor targets, such as fibroblast growth factor-2 (FGF-2) and its receptor FGFR-1, seem to promote tumor expansion and invasiveness through the concurrent activity on stromal and cancer cells." (PMID 28538690, 2017). "Addition of a single 6S did not significantly improve inhibitory properties of [NSIS]6 when tested against VEGF165-dependent endothelial cell functions.In vivo, [NSIS6S]-[NSIS]5 blocked FGF2-dependent blood vessel formation without affecting tumor growth." (PMID 27490176, 2016). "Integrins, particularly αvβ3, are involved in angiogenesis through interaction with vascular epithelial growth factor (VEGF) receptor, fibroblast growth factor 2 (FGF2), platelet-derived growth factor (PDGF), and matrix metalloproteinase-2 (MMP-2) which collectively aid tumor development and growth." (PMID 27556860, 2016). "A recent monoclonal antibody against FGF2 (GAL-F2) has shown promising anti-angiogenic and anti-tumour effects on a range of different hepatocellular carcinoma xenografts, and its effects could be increased by VEGF blockade." (PMID 26620208, 2016). "Indeed, several reports using different tumor models have shown that RTx can induce the expression of e.g. VEGF, FGF2 (bFGF) and PDGF." (PMID 27780936, 2016). "The interaction between SCF and CD117 might recruit mast cells in tumor tissue and make mast cells secret fibroblast growth factor-2 (FGF-2) and vascular endothelial growth factor (VEGF) and hence promote tumor growth." (PMID 27835573, 2016). "Tumour growth and tumour angiogenesis were both impaired, most likely due to the high titer of antibodies being raised against VEGF and FGF2 that could be detected in the blood." (PMID 26620208, 2016). "Interestingly, ligands for this receptor, FGF2, FGF17, FGF8, and FGF19, were also overexpressed in the tumour." (PMID 26998479, 2015). "Notably, miR-503 also prevents tumor growth by interacting with the tumor microenvironment and reducing secretion of the proangiogenic factors FGF2 and VEGF by tumor cells." (PMID 25860935, 2015).
tumor (continued). "The value of circulating levels of SDC1 was not consistently associated with tumor grade or characteristics, but the combination of SDC1 and bFGF/FGF2 in patient serum has a strong association with tumor progression and prognosis in selected cancer types." (PMID 26293675, 2015). "Furthermore, these collagen type I+/CXCR4+ cells were confirmed to produce FGF2, suggesting that the collagen type I+/CXCR4+ fibrocyte-like cells play an essential role in the bevacizumab resistance of tumours by expressing FGF2." (PMID 26635184, 2015). "These analyses demonstrated for the first time that Kapβ2 and Ran GTPase collectively facilitate the nuclear translocation of HMW-FGF2, which further potentiate the proliferation and survival of GBM tumor cells via activation of FGF2-downstream PTEN/Akt pathway." (PMID 26056081, 2015). "Fibrinogen can deposited around solid tumors and act as a stable framework to combine growth factors, such as fibroblast growth factor-2 (FGF-2) and vascular endothelial growth factor (VEGF), with tumor cells to increase the tumor proliferation and stimulate angiogenesis." (PMID 26600129, 2015). "The present study identifies the proteolytic cleavage of extracellular TFPI-2 by trypsinogen 4 as a new pathway regulating the response of tumor endothelial cell to the factors VEGF-A,FGF-2 and EGF (which characterize the angiogenic milieu), and hence tumor angiogenesis." (PMID 26318044, 2015). "The expression of BP1 in KS spindle cells, as well as infiltrating mononuclear cells located in close proximity to tumor vessels, strongly suggests that local production and release of BP1 functions to enhance the angiogenic activity of FGF-2 in these structures." (PMID 25429350, 2014). "Furthermore, miR-503, whose expression is down-regulated by hypoxia through HIF1α, also targets FGF2 and VEGFA for inhibiting tumor angiogenesis and growth." (PMID 24865854, 2014). "Moreover, BP1 reduces the binding affinity of FGF-2 for HSPGs and by this BP1 can amplify the angiogenic activity of FGF-2 in the KS tumor environment." (PMID 25429350, 2014). "VEGF has been shown to be upregulated by a number of other factors that are released in response to the rapid proliferation of tumor cells; these include transforming growth factor α (TGF-α), fibroblast growth factor 2 (FGF-2), and hepatocyte growth factor (HGF)." (PMID 24062983, 2013). "Some of these gene nodes have been shown to be functionally involved in other cancer types, including regulation of tumor cell proliferation (Creb, C/ebp, ATF3, ATF4), invasion (MTHFD2, FGF2) and metastasis (PTGS1/COX1, E-selectin, ATF3, FGF2, IL1A, MMP1, MMP13)." (PMID 24124450, 2013). "These increases suggest that a large tumor macrophage population promotes poor clinical outcome by potentiating aggressive CD30+ tumor cells in a subset of HL patients, and some of these CD30+ cells may express FGF2 and SDC1." (PMID 23988031, 2013). "Though 6-ME inhibited both VEGF- and FGF2-induced proliferation of ECs, we decided to study the effects of 6-ME only on VEGF-dependent EC responses, because VEGF is the most important mediator of tumor angiogenesis." (PMID 22583931, 2012). "It follows that down-regulation of HSULF-1 would enhance tumor growth, and it has been shown that over-expression of HSULF-1 in tumor cell lines inhibits specific, relevant signaling pathways dependent on growth factors including FGF-2, HB-EGF, HGF, and VEGF." (PMID 22873647, 2012). "The somatic cells of the testes secrete paracrine factors such as SCF, retinoic acid, FGF2, LIF, EGF and GDFN as well as androgenic hormones, and these might play a role in providing a tumor-promoting environment in the mouse." (PMID 22655094, 2012). "We found high FGF2 expression in tumor to be a significant independent negative prognostic marker in non-GIST STS patients with wide resection margins." (PMID 21733164, 2011).
tumor (continued). "FGF2 did not correlate with the clinical variables while low FGFR-1 expression correlated with small tumor size (low expression; < 50 mm 44%, 50-100 mm 34%, > 100 mm 22%, P = 0.005)." (PMID 21733164, 2011). "Indeed, heparin-binding proteins such as VEGF, FGF2, SDF-1α, HGF and P-selectin have been shown to mediate angiogenesis, tumor and host cell trafficking, tumor cell mobility and tumor cell seeding." (PMID 21698156, 2011). "In transformed tumor cell lines and in malignant tumors, overexpressed PTTG triggers production of FGF-2 and VEGF-A, cell cycle progression and angiogenesis, and in malignant tumors, high PTTG levels correlate with tumor invasiveness and serve as a marker of poor prognosis." (PMID 21464964, 2011). "These CAF-HI express higher levels of fibroblast growth factor 2 (FGF-2) than CAF from HD tumors (CAF-HD), and the exogenously administrated FGF-2 induced in vivo tumor growth of HD tumors in the absence of MPA." (PMID 20553594, 2010). "Experimental support for this model was the assembly of an FGF2 tertiary signaling complex in the tumor stroma but not on the surface of tumor cells." (PMID 20707913, 2010). "Importantly, inhibition of FGFR signaling via dominant-negative FGFR1, FGF2 neutralizing antibodies, FGFR TKI or anti-sense RNA approaches blocked proliferation of tumor growth in NSCLC." (PMID 21152424, 2010). "Among different “druggable” angiogenic factors, fibroblast growth factor-2 (FGF-2) is an attractive target for novel therapies because of its intricated involvement in tumor neovascularization, tumor cell proliferation and migration, and the acquisition of resistance to antiangiogenic therapies." (PMID 21317461, 2010). "In sum, our data show for the first time that a novel, 20-amino-acid peptide derived from the β chain of human Fgn, has a unique ability to inhibit the angiogenic responses of ECs to multiple GFs such as VEGF, FGF2, PDGF and HGF in vitro, and to inhibit tumour vascularisation in vivo." (PMID 20068569, 2010). "Similarly, tumor cells can recruit and activate stromal cells such as CAFs into the tumor microenvironment through secretion of pro-fibrotic growth factors such as TGF-α, TGF- β, FGF-2, and EGF." (PMID 41199904, 2025). "FGF1 and FGF2 belong to the FGF family, which possesses broad mitogenic and cell survival activities, and are involved in a variety of biological processes, including embryonic development, cell growth, morphogenesis, tissue repair, and tumour growth and invasion." (PMID 39940657, 2025). "However, as a possible side-effect, the tumor formation potential of these cells must be thoroughly investigated as part of the safety analyses, provided that EGF and FGF2 are also involved in tumor progression due to their proliferative actions on cancer cells." (PMID 40722636, 2025). "In fact, FGF2, also known as basic FGF (bFGF) due to its higher isoelectric point (positive charge) compared to other FGFs, is recognized as a critical factor in the maintenance of cancer stem cells (CSCs) and the tumor microenvironment due to its ability to bind both FGFR isoforms." (PMID 39796710, 2024). "In agreement with their capability of upregulating HIF-1, both VEGF and FGF-2 increase GLUT-1 expression in endothelial cells: as for FGF-2, it is likely that this can guarantee the optimal use of glucose via the nascent tumor vessels even in conditions of normoxia." (PMID 39120324, 2024). "With the advances in cellular and molecular biology, various biomolecules involved in tumor angiogenesis have been identified, such as vascular endothelial growth factor (VEGF), platelet-derived growth factor (PDGF), fibroblast growth factor 2 (FGF-2), chemokines, ephkrine, apelin (APLN)." (PMID 39518052, 2024).